TNF (tumor necrosis factor)
Diseases named in the same sentence as TNF in open-access papers (continued):
Sharing a sentence is not in itself a finding about the gene and the disease.
depression (continued). "The results indicated that compared to controls, patients typically have higher inflammatory biomarkers (i.e., TNF-alpha, TNFR1, TNFR2, CRP, IL-1ra) and worse fatigue, depression, and sleep (ps < 0.05)." (PMID 37444517, 2023). "The effect of CBT on suppressing inflammation has been demonstrated in depression by lowering at least one of the inflammatory markers out of CRP, IL-6, and TNF-α." (PMID 37163444, 2023). "Cytokines, which mediate the innate immune response, including IL-1, tumor necrosis factor (TNF)-alpha, C-reactive protein (CRP), and IL-6, from peripheral blood are considered the most reliable biomarkers of inflammation in patients with depression." (PMID 37065487, 2023). "Inflammatory cytokines, such as IL-1β, TNF- α and IL-6 but also HPA axis imbalanced regulation of glucocorticoids, are mainly present in depression and anxiety patients." (PMID 37764111, 2023). "First, pro-inflammatory cytokines such as IL-6 and TNF impair the expression of BDNF, leading to the onset of depression." (PMID 36978923, 2023). "Elevated levels of inflammatory markers such as IL-1β, IL-6, IL-2, TNF-α, CRP and PGE2 were found in patients with depression." (PMID 37387537, 2023). "Several systemic reviews and meta-analysis studies on the correlation between cytokines level and depression, anxiety, and PTSD showed evidence of higher levels of IL-1, IL-6, and TNF-α in individuals with Major Depressive Disorder (MDD), anxiety, and PTSD compared to controls." (PMID 37388279, 2023). "Elevated levels of neuroinflammatory cytokines such as interleukin (IL)-1β, tumor necrosis factor-α (TNF-alpha) and IL-6 have been identified in patients with depression." (PMID 36829840, 2023). "Results revealed that the classical pro-inflammatory cytokine TNF-α (p = 0.0011) and also the CCL2 chemokine (p = 0.0453), were significantly upregulated in depression patients compared with healthy controls." (PMID 37575572, 2023). "And a large number of studies have shown that depressed patients with depression have C-reactive protein (CRP), prostaglandins, and other arachidonic acid derivatives, as well as IL-6, IL-1β and TNF-α were significantly increased." (PMID 37492068, 2023). "In particular, it was shown that the levels of some inflammatory cytokines (i.e., IL-6, IL-1, TNF-α, etc.)were significantly increased in the serum of MDD patients and in the brain of rodent models of depression." (PMID 37298063, 2023). "It is well known that activated microglia release pro-inflammatory mediators and oxidative products such as IL-1β, TNF-α, and MDA, which promote neuronal damage and induce the development of depression." (PMID 36793870, 2023). "Cytokines such as IL-1β, IL-6, TNF-α, and IFN-γ are known for their importance in depression mechanisms." (PMID 37834806, 2023). "TNF-α, IFN- α, IL-1, IL-1β and IL-6 are mostly found with increased concentrations in the serum of depression and anxiety patients." (PMID 37764111, 2023). "In this study, we found an upregulation of TNF-α and CCL2 levels in the plasma of depression patients." (PMID 37575572, 2023). "In the current study, a positive correlation was found between TNF-α, IL-6, IL-8, and IL-17A after AIS onset and anxiety, depression, or cognitive impairment at different time points." (PMID 37878890, 2023). "The patients showed a significant increase in the levels of inflammatory markers IL-1β (p < 0.001), TNF-α (p < 0.001), and CRP (p < 0.001), despite improvement in PTSD (p < 0.001) and depression (p < 0.001) symptoms from baseline through one year follow-up." (PMID 37081449, 2023). "Antidepressant agomelatine (AGO) eliminated depression in HFD rats, reduced the activity of inflammatory cytokines (TNF-α, IL-6, and IL-1β), TABRS, and restored the activity of CAT and GPX." (PMID 37108261, 2023).
depression (continued). "The biological link between depression and CVD may be related to the overactivation of the hypothalamic−pituitary−adrenal axis results in the dysregulation of immune system and further causes high levels of proinflammatory cytokines (such as IL‐1β, TNF‐α, and IL‐6) released by macrophages." (PMID 37593998, 2023). "Several groups including ours have identified the roles of inflammation-related molecules, such as IL-1β, TNF-α, and PGE2, for depression-related behaviors in a mouse model of chronic stress, which has often been used to study depression." (PMID 37443823, 2023). "In this context, wormwood decreased tumor necrosis factor alpha levels and the CD activity index score, whilst scores for IBD questionnaire and Hamilton depression scale have been improved, compared to the controls." (PMID 37841934, 2023). "It has been confirmed that using anti‐TNF‐α blockers can be a probable way to help depression in unresponsive patients with PSD, where common therapies like SSRIs have shown higher levels of TNF‐α in before and posttreatment." (PMID 36655100, 2023). "Consistent with the “depression-inducing” effects of pro-inflammatory cytokines, particularly TNF-α, several lines of evidence attested to the efficacy of selective TNF-α antagonists as a potential treatment for depression." (PMID 37511030, 2023). "IL-1, TNFα, IFNγ, NGF, or microglia activation in depression, as well as IL-4, TNFα, and IL-10 in mania, were normalized by celecoxib in preclinical studies." (PMID 37240605, 2023). "Again, systemic inflammation (such as in metabolic syndrome) has been suggested to alter the brain DA circuit involved in depression and anhedonia, with the CNS modulation of IFN, IL1, IL6, TNFα, and COX2 levels, as a supposed critical role for TNFα and IL6." (PMID 37511235, 2023). "The most pertinent point is that pro-inflammatory cytokines such as IL-6 and TNF impair the expression of BDNF, which leads to the onset of depression." (PMID 36978923, 2023). "Serum level analysis of cortisol, DHEA, TNF-α, IL-6, IL1β in 12 women with BPD and depression (age: 25.6 (3.9)), compared to 12 healthy women (age: 26.3 (5.1))." (PMID 36946840, 2023). "Proinflammatory cytokines, involving TNFα, IL1β, IL6, and interferon, are important regulators in the pathogenesis of depressive disorder." (PMID 38273824, 2023). "In particular, IL-1β, IL-2, IL-6, TNF-α and IFN-γ are reported to be involved in cytokine-induced depression." (PMID 36045388, 2022). "Isolated mitochondria significantly reduced hippocampal astrocyte and microglia activation and neuroinflammation (i.e., 1L-1β, TNF-α, and COX-2), increased BDNF expression, and restored ATP production dysfunction and oxidative stress in LPS-induced depression." (PMID 36440427, 2022). "IDO1, a therapeutic target in depression, metabolizes tryptophan to KYN and is upregulated during pro-inflammatory states induced by several cytokines (IL-1β, IL-6, IFN-α, TNF-α)." (PMID 35501309, 2022). "COX-2 inhibition has also been shown to influence IL-1β, TNFα, and PGE, and thereby modulate clinical symptoms of depression." (PMID 35415080, 2022). "As was revealed in several experiments in animal models of depression, quercetin exerted antioxidant (reducing ROS, increasing SOD, GST, GSH activity) as well as anti-inflammatory activity (suppressing IL-1β, IL-6, TNF-α, COX-2, microglial activation)." (PMID 35455082, 2022). "Here, in a mouse model of depression, FPF ameliorated SD stress-induced depression-like behavior, reducing SD-stress-elevated plasma ACTH and corticosterone levels and TNF-α and IL-1β mRNA expression." (PMID 36614066, 2022). "FA and serum cytokines (IL-1β, IL-6, TNF-α, and IFN-γ) were measured in 25 patients with depression (DE) and 24 healthy controls (HC)." (PMID 36261698, 2022). "Increased levels of tumor necrosis factor-alpha (TNF-α) and interleukin-6 (IL-6) in cerebrospinal fluid and brain parenchyma were detected in patients with depression." (PMID 35036964, 2022).
depression (continued). "A study revealed that the levels of interleukin-6 (IL-6), tumor necrosis factor-alpha (TNF-α), and interleukin-8 (IL-8) were increased in cerebrospinal fluid (CSF) of patients with depression." (PMID 36844911, 2022). "With the development of the cytokine theory of depression, it has been well documented that pro-inflammatory cytokines, including IL-1β, IFN, and TNF can reduce the bioavailability of neurotransmitters such as serotonin (5-HT)." (PMID 36232376, 2022). "Based on the network topology combined with the PPI analysis, we obtained that TCEF can regulate depression through five core targets, namely, ALB, AKT1, TNF, ESR1, and CTNNB1." (PMID 36506595, 2022). "The tumor necrosis factor (TNF), a central component of the innate type of immune system, is one of the most common cytokines studied in depression." (PMID 36325528, 2022). "Research has demonstrated positive correlations between cytokines interleukin (IL)-6 and tumor necrosis factor (TNF)-α and symptoms of depression in meta-analyses of both community samples and adults diagnosed with major depressive disorder (MDD)." (PMID 35651828, 2022). "In a meta-analysis that compared 5166 patients with depression and 5083 controls, patients with depression exhibited a significantly higher pro-inflammatory state (i.e., higher levels in CRP, L-3, IL-6, IL-12, IL-18, sIL-2R, and TNFα) than controls." (PMID 35682203, 2022). "Meta-analytic research has shown that patients with major depressive disorder (MDD) have significantly higher serum IL-6 and TNF-α levels than healthy controls." (PMID 35624812, 2022). "Our study firstly revealed a significant mediating effect of TNF-α between E-DII and DepS, extending new evidence that inflammation mediates the relationship between diet and depression." (PMID 36615742, 2022). "Inflammatory cytokines (IL-6 and TNF-α), inflammatory diet (Diet Inflammatory Index; DII), and depressive symptoms (Beck Depression Inventory-II; BDI-II) were measured in 136 females (Mage = 22.01 ± 4.02, range 18–59 years)." (PMID 35651828, 2022). "The Young Manic Rating Scale (YMRS), Self-Rating Depression Scale (SDS), and Interleukin-6 (IL-6), Tumor necrosis factor-α (TNF-α) and C-reactive protein (CRP) levels will also be measured." (PMID 36458119, 2022). "TNF-α, IFN-γ, IL-5, IL-12 and IL-13 were also related to the severity of depressive symptoms, as well as the somatic–affective and cognitive dimensions of depression." (PMID 35407580, 2022). "At baseline, TNF-α (F = 36.699, p < 0.001), IFN-γ (F = 8.907, p < 0.001), IL-4 (F = 66.256, p < 0.001), and IL-2 (F = 9.162, p < 0.001) levels in the depression group were significantly different from those of healthy controls." (PMID 35722555, 2022). "We also examined the mRNA level of inflammation-related factors, including IL-1β, IL-6, TNFα, and IL-10 in the PFC, dorsal hippocampus, and ventral hippocampus, which are three critical regions of the brain that are related to anxiety and depression." (PMID 35684068, 2022). "Furthermore, TNF‐α, IL‐1β, IL‐6, and IL‐17 were all positively associated with HADS‐A score (all P < 0.05), anxiety occurrence (all P < 0.05), HADS‐D score (all P < 0.05), and depression occurrence (all P < 0.05) in NSCLC survivors, while the correlation‐coefficients were weak." (PMID 34697903, 2022). "UHPLC-Q-EOMS was employed to identify 59 major components of TCEF, and network pharmacology analysis was used to screen 48 active components of TCEF for treating depression, corresponding to 139 relevant targets, including ALB, AKT1, TNF, ESR1, and CTNNB1." (PMID 36506595, 2022). "Proinflammatory cytokines, including interleukin-6 (IL-6) and tumor necrosis factor-alpha (TNF-α), have been found to be higher in patients with major depressive disorder, while their antioxidant capacity is lower." (PMID 36339940, 2022).
depression (continued). "It has been shown that the inflammatory factors IL-1β, IL-6, TNF, and C-reactive protein (CRP) in peripheral blood are reliable biomarkers for patients with depression." (PMID 36186850, 2022). "The levels of IL-4, IL-10, T, and NPY in depression patients, DCMI patients, and CUMS + LPS model rats elevated, while the levels of IL-1β, IL-6, and TNF-α were reduced." (PMID 35432561, 2022). "Among the multiple signaling pathways associated with the p-CA anti-depression function, predicted by the KEGG analysis, inflammation-related signaling pathways, such as TNFα, NF-kB and VEGF signaling pathways, have been well elucidated in depression." (PMID 35626632, 2022). "With significantly improved depression symptoms, the post-treatment hs-CRP, TNF-α, and IL-6 levels in the drug naïve patients with MDD were lower than that in the HC." (PMID 35911989, 2022). "The AGE-RAGE signaling pathway mediates NF-kB activation and upregulates the expression of proinflammatory cytokines (e.g., IL-1β, IL-6 and TNFα) and growth factors (e.g., VEGF), which contribute to depression development and progression." (PMID 35626632, 2022). "Our results revealed that the administration of conventional coffee and decaffeinated coffee ameliorated depression-like behaviors in rats of PSD induced, as well as the changed levels of IL-6, TNF-α, SOD, and GSH-Px." (PMID 35283829, 2022). "Further studies found that KXS can reduce glucocorticoid secretion by regulating the levels of serum cytokines (such as COX, IL-2, and TNF-α) while inhibiting HPA axis hyperactivity and inhibiting apoptosis and thus treating depression." (PMID 36440427, 2022). "Furthermore, high TNF-α (P=0.044, P=0.176 after adjustment), high IL-1β (P=0.012, P=0.048 after adjustment), increased IL-6 (P=0.010, P=0.040 after adjustment), and increased IL-17 (P=0.010, P=0.040 after adjustment) were correlated with increased depression severity grade." (PMID 35239774, 2022). "A recent metanalysis reported an increase in systemic pro-inflammatory cytokines, IL-1, IL-6, TNF-alpha and C-reactive protein (CRP) in depression patients." (PMID 35323251, 2022). "Clinical evidence showed that inflammatory mediators were elevated in patients with depressive disorder, such as HMGB1, IL‐1β, TNF‐α, CRP, IL‐6, and so on." (PMID 35089644, 2022). "The findings in this study do not support a role of CNS inflammation, as measured by altered CSF levels of IL-6, IL-8, TNF-α, IL-10, MCP-1 or TGF β, in geriatric patients with depressive disorders." (PMID 36172507, 2022). "Lastly, the group with type 2 diabetes also used less alcohol, were less physically active, had a higher prevalence of depression, a history of CVD and cognitive impairment and higher plasma concentrations of IL-6 and TNF-α compared with those with NGM." (PMID 34409496, 2021). "In conjunction with measures of pregnancy-specific anxiety and depression, serum biomarkers (IL-2, IL-6, IL-10, IL1-B, TNF-α, CRH, CRP, and cortisol) were analyzed for each trimester throughout pregnancy." (PMID 34360332, 2021). "Chronic unpredictable mild stress can induce depression in mice and increase serum cytokines such as IL-1β, IL6, and TNFα." (PMID 34082798, 2021). "Another reason for increased TNF-α and IL-6 in the serum in this study was the occurrence of CUMS-induced depression as they have been reported to be elevated in patients with depression and mice showing behavioral despair." (PMID 34040528, 2021). "Two meta-analyses showed reliably higher levels of inflammatory markers in depression, namely IL-1β, IL-6, C-reactive protein (CRP), and TNF-α." (PMID 34975571, 2021). "Elevated levels of various inflammatory biomarkers, such as IL-6 and TNF-α, and increased high-sensitivity C-reactive protein (CRP) concentrations were found to be present in patients with mild to moderate depression six months following stroke." (PMID 34471414, 2021).
depression (continued). "Basic studies demonstrated that modified BXXXD, a formula similar to GJHQHLRSD, can effectively alleviate UC as well as relieve depression and UC through targeting VEGFA, TNF, STAT3, EGFR, and others." (PMID 34539797, 2021). "The present study demonstrates that the higher the ratio TNF-α/BDNF, the greater the severity of depression." (PMID 34841285, 2021). "It has been widely reported that the up-regulated pro-inflammatory cytokines, such as tumor necrosis factor-α (TNF-α), interleukin-6 (IL-6) and IL-1β are related to depression/anxiety-like behaviors." (PMID 34977127, 2021). "The use of anti-TNF-α in case of coexistence with other immune-mediated and inflammatory diseases such as IBD, depression, multiple sclerosis, is also complex." (PMID 34829740, 2021). "Second, clinical evidence has indicated that VNS is associated with marked peripheral increases in pro- and anti-inflammatory circulating cytokines, such as IL-6, TNF-α, and TGF-β in patients with resistant depression." (PMID 34526917, 2021). "A recent study found an association between the downregulation of 20 genes related to the apoptosis pathway, TNF-α, TLR, and NFκβ signaling pathways and major depressive disorder." (PMID 34295268, 2021). "In this context, increased production of TNF-α and decreased levels of the anti-inflammatory mediator transforming growth factor-β (TGF-β) have been considered as neurobiological links between depression and AD." (PMID 33922780, 2021). "The target-pathway network illustrated that AKT1, MAPK1, GSK3B, TNF, MTOR, and PTEN were core targets enriched in key signaling pathways that played crucial roles in the treatment of depression by CCHP." (PMID 34976096, 2021). "Another study has shown rapid decreases in levels of IL-6 and TNF-α, as well as a correlation between the decrease in TNF-α and a reduction in the Montgomery–Asberg Depression Rating Scale (MADRS) score." (PMID 34248517, 2021). "The KBD formula normalized UMCS-induced anhedonia and hopeless behaviors in mice by restoring expression of the depression-related genes BDNF, CREB, GR, SGK1, FKBP5, IL-1β, IL-6, and TNF-α in the frontal cortex and hippocampus brain regions." (PMID 34358084, 2021). "We examine the relation, interaction, and ratio between the neurotrophic brain-derived neurotrophic factor (BDNF) and the proinflammatory cytokines interleukin-6 (IL-6) and tumor necrosis factor α (TNF-α), and depression severity during ECT." (PMID 34841285, 2021). "A variety of proinflammatory cytokines such as IL-1β, IL-6, TNF, and Toll-like receptor 3 (TLR3) has been found to overexpress depression." (PMID 34650925, 2021). "The pro-inflammatory cytokines such as interleukin-6 (IL-6), interleukin-1β (IL-1β), and tumor necrosis factor-α (TNF-α) in peripheral and central nervous system are significantly increased in patients with depression." (PMID 34772918, 2021). "We performed GO enrichment and KEGG pathway analyses, which showed that activity of HE compounds were associated with various neurochemical processes that are dysregulated in depression, including MAPK, IL-17, TNF and neurotrophin signalling." (PMID 34876186, 2021). "Metaanalyses have shown higher concentrations of cytokines such as IL1ß, TNFα, and IL6 in the peripheral blood of patients with depression compared to healthy controls." (PMID 34773692, 2021). "In patients with depression and AD raised levels of pro-inflammatory cytokines, acute phase proteins (APPs), interferon gamma (IFN-γ), interleukin 1 (IL-1), IL-6, and TNF-α were observed." (PMID 34573069, 2021). "In the present study IL-6, TNF-α, BDNF, and depression severity before, during, and after ECT were examined in LLD." (PMID 34841285, 2021). "Investigations of serum levels of tumor necrosis factor-α (TNF-α) in depressed patients have previously shown contradictory results of increased and decreased levels of TNF-α during the treatment of depression." (PMID 34257748, 2021).